HGF (hepatocyte growth factor)
Diseases named in the same sentence as HGF in open-access papers (continued):
Sharing a sentence is not in itself a finding about the gene and the disease.
lung carcinoma (continued). "In the present study, we examined whether the clinically approved mTOR inhibitors, temsirolimus and everolimus, circumvent HGF-triggered EGFR-TKI resistance in EGFR mutant lung cancer cells using in vitro and in vivo models, and assessed underlying mechanisms." (PMID 23690929, 2013). "Our studies showed that bufalin could reverse resistance to reversible and irreversible EGFR-TKIs induced by exogenous HGF in EGFR mutant lung cancer cells by inhibiting the Met/PI3K/Akt pathway and inducing death signaling." (PMID 23533466, 2013). "TAM isolated from 98 primary lung cancer tissues shows the higher ability to produce HGF." (PMID 23296269, 2013). "In addition, HGF stimulates VEGF production by EGFR mutant lung cancer cells, as well as facilitates angiogenesis, thereby promoting tumor progression." (PMID 23690929, 2013). "To determine how frequently ligands that initiate signaling of both pathways are found in lung cancer, we analyzed serum for hepatocyte growth factor (HGF), transforming growth factor-alpha, and amphiregulin (AREG) in lung cancer cases and tobacco-exposed controls." (PMID 21390244, 2010). "In specific, when two human lung cancer cell lines, A549 and PC-9, were treated with curcumin, a dose-dependent decrease in the expression of Akt and mTOR was observed as a result of the inhibition of hepatocyte growth factor (HGF) and its downstream effector c-Met." (PMID 38672636, 2024). "Interestingly, some incoming signaling pathways were found to be specific to one subtype of lung cancer, as exemplified by HGF (a new highlight in the treatments of lung cancer), KIT (activating the JAK/STAT and PLC/PKC signaling pathways) in LUAD, and the CSF3 and CDH5 in LUSC." (PMID 36008393, 2022). "It was indicated that HGF may serve as a target of miR-144-3p during development of lung cancer." (PMID 35568918, 2022). "Therefore, we speculate that the mechanism of elemene in reversing the resistance of lung cancer PC-9 cells to gefitinib may be related to the inhibition of c-Met and its downstream signaling pathways activated by HGF." (PMID 34641334, 2021). "Cinobufotalin combined with gefitinib suppresses A549 cell viability and promotes cell apoptosis by downregulating HGF protein expression and blocking c-Met gene amplification, indicating that cinobufotalin may delay the occurrence of gefitinib resistance in lung cancer cells." (PMID 34122599, 2021). "Moreover, our results indicated that cortactin expression was upregulated when lung cancer cells were treated with PDBu or HGF, as well as invadopodia formation in non-small cell lung cancer cells, which indicated an important role of cortactin in invadopodia formation." (PMID 29986736, 2018). "However, another study found decreased serum HGF levels in lung cancer patients." (PMID 28121629, 2017). "Importantly, curcumin reversed HGF-induced EMT markers changes, causing reinduction of E-cadherin and reinhibition of vimentin expression in a concentration dependent manner, indicating that curcumin has inhibitory effects on HGF-induced lung cancer cell EMT." (PMID 27525306, 2016). "Therefore, we demonstrated that curcumin inhibits HGF-induced EMT in lung cancer cells." (PMID 27525306, 2016). "Moreover, HGF increases cisplatin resistance via activation of MET in lung cancer cells." (PMID 27014910, 2016). "However, LY294002 only inhibited p-Akt and p-mTOR, and rapamycin only inhibited p-mTOR, indicating that c-Met/PI3K/Akt/mTOR signaling is a key pathway that involved in the roles of HGF in lung cancer, and might be also the main target of curcumin." (PMID 27525306, 2016). "Hence, HGF and these molecules may be targets for intervention of drug-resistant lung cancer and combination of targeting two or more molecules may be valuable for intervention of drug-resistant lung cancers." (PMID 26115510, 2015).
lung carcinoma (continued). "In our previous Japanese cohort study of patients with EGFR mutant lung cancer, high HGF expression was detected in 61% of tumors with acquired resistance and in 29% of tumors with intrinsic resistance to EGFR-TKIs, suggesting that targeting HGF may overcome resistance to EGFR-TKIs." (PMID 24386407, 2013). "HGF may induce resistance to EGFR-TKIs in EGFR mutant lung cancer cells by Met/PI3K/Akt signaling." (PMID 23533466, 2013). "HGF could induce resistance to EGFR-TKIs via Met/PI3K/AKT activation, indicating that to overcome resistance to EGFR-TKIs induced by HGF-triggered activation of Met/PI3K/AKT pathway in mutant lung cancer, it was necessary to double blockade EGFR and HGF-Met signaling pathways." (PMID 23533466, 2013). "Indeed, the class I PI3K-mTOR inhibitor PI-103 was able to induce apoptosis in EGFR-mutant lung cancer cells that initially showed hepatocyte growth factor (HGF)-induced resistance to EGFR-TKIs and in combination with the EGFR inhibitor gefitinib, halt the tumor growth in murine xenograft models." (PMID 24281308, 2012). "Furthermore, EGFR ligands can activate c-Met independently of HGF in lung cancer cells, allowing for signaling via HGF-dependent and HGF-independent mechanisms both of which may contribute to c-Met mediated effects." (PMID 21390244, 2010). "Mesenchymal-epithelial transition (MET) is the receptor for hepatocyte growth factor (HGF), and its role in promoting lung cancer progression has been well-documented." (PMID 40867310, 2025). "As in lung cancer, pancreatic cancer cells are also positively regulated by the feedback loop between FOXM1 and hepatocyte growth factor (HGF)/MET signaling." (PMID 39594778, 2024). "The regulation of ENO1 directly activates HGF-MET signaling and Wnt-LRP5/6, in a manner indirectly driven by an EMT phenotype in studied lung cancer models." (PMID 37381723, 2023). "We previously reported that hepatocyte growth factor (HGF), predominantly produced by fibroblasts, plays an important role in lung cancer cell lines that are resistant to EGFR‐TKIs." (PMID 36416133, 2023). "Among the most interesting studies conducted in the last 10 years, CancerSEEK reported a panel of eight proteins (CA-125, CEA, HGF, Myeloperoxidase, OPN, Prolactin, and TIMP-1) effective in distinguishing lung cancer patients from healthy controls." (PMID 38068296, 2023). "In the treatment of lung cancer, one of the molecular targets is EGFR/ERBB1, belonging to the RTK (receptor tyrosine kinases) family, and Met/HGF, also known as hepatocyte growth factor." (PMID 37373500, 2023). "FoxF1, a downstream effector of HH signaling, stimulates the secretions of HGF and FGF2 by lung cancer fibroblasts, promoting lung cancer cell growth and migration in vivo." (PMID 35433472, 2022). "HGF also encourages the phosphorylation of c-MET, thus facilitating the generation of gefitinib resistance in lung cancer." (PMID 36359776, 2022). "Hepatocyte growth factor (HGF) is the ligand of the proto-oncogene c-Met; it can trigger MET activation through EGFR bypass signaling and induce lung cancer resistance to EGFR-TKIs." (PMID 35840984, 2022). "Strategies that lead to acquired EGFR-TKI resistance, such as HGF, MET amplification, and EGFR T790M, also promote immune escape in lung cancer by upregulating the expression of PD-L1." (PMID 35840984, 2022). "For example, in the anti-EGFR target therapy using gefitinib for lung cancer, MET (receptor of HGF) amplification leads to resistance by activating ERBB3 signaling." (PMID 35625759, 2022). "In lung cancer, PMPs stimulated the generation of MMPs, VEGF, IL-8 and hepatocyte growth factor (HGF), which were common angiogenic regulators for metastasis." (PMID 34722319, 2021). "The protein expression of HGF, PTX3, and S100P in lung cancer tissues and normal lung tissues was validated using the HPA online database." (PMID 34745947, 2021).
lung carcinoma (continued). "This project, therefore, aimed to evaluate the interaction between SIPA1 and HGF/MET, as well as their influence on lung cancer in terms of molecular activation, cellular behaviour and clinical relevance." (PMID 33917539, 2021). "In order to further explore the impact of the HGF/c-MET pathway on tumors, we conducted some experiments in vitro in lung cancer and esophageal cancer cell lines." (PMID 34261467, 2021). "The seed sequences of miR-1 and miR-206 are identical, and both inhibited c-Met and the downstream Akt and Erk pathways, and HGF-induced EMT, and increased gefitinib sensitivity in lung cancers." (PMID 32219093, 2020). "Platelet-derived microvesicles have been shown to transfer CD41 (as known as integrin α-2b) to the surface of lung cancer cells, which in turn induced expression of pro-angiogenic cytokines such as VEGF, IL-8, and hepatocyte growth factor (HGF)." (PMID 32751440, 2020). "Therefore, we hypothesized that AP-1 is involved in HGF-induced PD-L1 expression in lung cancer." (PMID 31747941, 2019). "Here, we show that miR-16 levels in lung fibroblasts control HGF production in an FGFR1-dependent manner unraveling a novel mechanism of communication between stromal and neoplastic cells in lung cancer, with potential clinical implications." (PMID 29558956, 2018). "Not only is the expression of slug regulated by EGFR signaling pathway but also it is induced by hepatocyte growth factor (HGF)/c-Met-mediated signaling pathway in murine colorectal and lung cancer cells." (PMID 29681982, 2018). "In this study, we showed that miR‐1‐3p and miR‐206 restored the sensitivities of lung cancer cells PC‐9 and HCC‐827 to gefitinib in present of HGF." (PMID 29664235, 2018). "HGF‐dependent MET activation via endocrine, paracrine or autocrine signaling had been observed in lung cancer." (PMID 29570930, 2018). "HGF has been shown to block the response of lung cancer cells to EGFR targeting drugs and increased levels of serum HGF predict poor progression-free survival and overall survival in NSCLC patients treated with EGFR inhibitors." (PMID 28968967, 2017). "We previously reported that lung cancer cell lines had increased expression of c-MET due to gene amplification-induced cytotoxic drug resistance, and that resistant cells paracrine HGF and promote its resistance." (PMID 29069748, 2017). "While HGF-activating enzymes are upregulated in lung cancer, the levels of HAI-1/2 are commonly reduced in cancer tissue, resulting in increased activation of HGF." (PMID 28968967, 2017). "Recent studies showed that CX4945 induced down-regulation of the autophagosome-mediated EGFR in lung cancer, while EGFR inhibitors induced, in lung adenocarcinoma, activation of the HGF/Met pathway as a mechanism of drug resistance." (PMID 28873435, 2017). "In lung carcinoma cells, ATA treatment inhibited HGF-induced c-Met phosphorylation and subsequent cell migration." (PMID 28103571, 2017). "Here we established that SRI31215, and peptide-based inhibitors of pro-HGF activation, block the tumor-promoting activity of fibroblasts and overcome the resistance of MET-amplified lung cancer cells to anti-MET therapy." (PMID 28968967, 2017). "HGF was produced to a greater extent by the three fibroblasts (2.2, 7.1, and 3.4 ng/mL in HFL1-, MRC5-, and IMR90-media, respectively) than by lung cancer cells." (PMID 28619066, 2017). "HGF-producing fibroblasts promote the survival and migration of MET-amplified lung cancer cells when MET is inhibited." (PMID 28968967, 2017). "The aim of this study was to investigate the potential of curcumin to inhibit HGF-triggered EMT and angiogenesis in lung cancer cells in vitro and in vivo." (PMID 27525306, 2016). "Taken together, miR-206 inhibits HGF-induced EMT and angiogenesis in lung cancer by suppressing c-Met/PI3k/Akt/mTOR signaling." (PMID 26919096, 2016).
lung carcinoma (continued). "To determine the effect of HGF on EMT and metastasis of lung cancer, we examined the morphology, EMT markers expression, migration and invasive abilities of lung cancer cells after HGF stimulation." (PMID 26919096, 2016). "Both HGF and its receptor, the MET tyrosine kinase, are overexpressed in lung cancer and as such are targets for therapeutic interventions." (PMID 25884481, 2015). "High level of HGF was detected in the monoculture supernatants from the MRC5 fibroblasts and the primary lung TAFs and in the co-culture supernatant of lung cancer cells (H596) with MRC% fibroblasts or the primary lung TAFs." (PMID 26053043, 2015). "CAFs also secrete hepatocyte growth factor (HGF), which not only activate EMT-related c-Met pathway but also give lung cancer cells resistance to conventional epidermal growth factor tyrosine kinase inhibitors." (PMID 25937967, 2014). "Cell models used included Hep3B, C3A, HepG2 and Huh7, several of which showed an upregulation of erlotinib-resistance genes, AXL, HGF, FGFR1 and ERBB3 in comparison to an erlotinib-sensitive lung cancer line." (PMID 24551227, 2014). "This antibody inhibits the growth and invasion of different tumor cell lines, and shows a potent anti-tumor effect in in vivo models of both HGF-dependent and HGF-independent MET activation, including a MET-amplified lung cancer xenopatient." (PMID 28548076, 2014). "In lung cancer, CAFs express CCR5 and are activated by CCL3 to secrete hepatocyte growth factor (HGF) to accelerate angiogenesis." (PMID 25110692, 2014). "Crizotinib activity has been reported in MET-amplified tumors, with ongoing studies in EGFR TKI-resistant lung cancer of MET and HGF-targeted agents, such as ficlatuzumab (anti-HGF monoclonal antibody, NCT02034981)." (PMID 25505733, 2014). "HGF, the sole ligand of Met, is important in the development of EGFR-TKI resistance in EGFR mutant lung cancer cells." (PMID 24386407, 2013). "The concentrations of HGF in peripheral blood were found to be inversely correlated with clinical responses to EGFR-TKIs in both EGFR mutant and wild-type lung cancer." (PMID 23533466, 2013). "We previously reported that HGF activates the MET/GAB1 pathway and increases VEGF production by EGFR mutant lung cancer cells." (PMID 23690929, 2013). "MET, the receptor tyrosine kinase for hepatocyte growth factor (HGF) has been shown to drive tumorigenesis when overactivated in a number of cancers, including lung cancer." (PMID 23300999, 2013). "Both temsirolimus and everolimus inhibited the phosphorylation of p70S6K and 4E-BP1, which are downstream targets of the mTOR pathway, and reduced the viability of EGFR mutant lung cancer cells, PC-9, and HCC827, even in the presence of HGF in vitro." (PMID 23690929, 2013). "EGF-receptor tyrosine kinase (TK) inhibitors, such as Gefitinib, are known to reduce lung carcinoma metastasis, but long-term use of Gefitinib leads to drug resistance via MET gene amplification or HGF-dependent pathway." (PMID 23296269, 2013). "In lung cancer, resistance to EGFR TKIs correlates with amplification of the hepatocyte growth factor (HGF) receptor tyrosine kinase Met." (PMID 22788954, 2012). "For example, CAFs can over‐secret ANXA2, which triggers EMT in lung cancer cells; this pro‐EMT phenotype is dependent on the secretion of hepatocyte growth factor (HGF) and insulin‐like growth factor 1 (IGF1) by CAFs, thus facilitating the cancer cells' evasion of EGFR targeting." (PMID 40162549, 2025). "Interestingly, HGF/c-Met Axis, VEGF signaling, and PI3K/AKT pathway are all involved in the proliferation, growth, and metastasis of lung cancer cells, and they are all identified as effective therapeutic targets in lung cancer." (PMID 36947712, 2023). "Hepatocyte growth factor (HGF) promoted EMT in meningioma, lung cancer, and oral cancer cells." (PMID 37446730, 2023).
lung carcinoma (continued). "HGF enhanced expression of glucose transporters GLUT-1 and GLUT-4 in myocytes, increased glucose consumption and lactate production in a breast cancer model, and induced hexokinase 2 (HK2) expression in a lung cancer model." (PMID 31940827, 2020). "However, it is also well known that FAK can be activated by extracellular growth factors, including those released by lung cancer, such as bombesin, gastrin-related peptide (GRP), HGF, VEGF, TGF-β, HGF, and FGF." (PMID 31658694, 2019). "A novel molecular mechanism was shown that HAI-2 serves as a novel non-covalent inhibitor of plasmin and suppresses the protease-induced activations of pro-HGF, pro-TGF-β1 and MMP-2/9 as well as ECM degradation, leading to reducing lung cancer cell motility, EMT, and metastasis." (PMID 30765871, 2019). "Similarly, HGF-producing human fibroblastic cells confer resistance to gefitinib, a TKI selective to EGFR in lung cancer cells through the PI3K/Akt signal pathway." (PMID 31067787, 2019). "Simultaneous blockade of the two approaches with EGFR-TKI and HGF-MET antagonists could resist the drug resistance and accelerate the successful treatment for lung cancer patients to the full extent." (PMID 29455669, 2018). "HGF, known as the ligand of MET, is primarily produced by lung cancer cells and stromal cells." (PMID 29455669, 2018). "HGF may also play a role in governing MMP-9 expression levels, as HGF antagonists have demonstrated the ability to downregulate MMP-9 activity in lung cancer cells." (PMID 30314527, 2018). "Additionally, we used an A549 lung cancer cell line, which has been previously demonstrated to secrete no detectable level of HGF but could potentially promote c-Met activation in response to HGF, for further assessment of cellular proliferation in the presence of IRCR201." (PMID 28902178, 2017). "Although transforming growth factor-β is known to change the characteristics of lung fibroblasts and is produced by lung cancer cells, its exogenous addition did not stimulate HGF production by fibroblasts (data not shown)." (PMID 28619066, 2017). "In this study, we revealed that enhanced expression of miR-206 could reverse HGF-induced EMT and angiogenesis in lung cancer through inhibiting c-Met/Akt/mTOR pathway." (PMID 26919096, 2016). "In conclusion, overexpression of miR-206 could not only inhibit HGF-induced EMT, migration and invasion of lung cancer cells, but also reduce migration and tube formation of HUVECs." (PMID 26919096, 2016). "Since it has been demonstrated that HGF induces EMT, migration and invasion of lung cancer cells, we next determined whether miR-206 regulates HGF-induced EMT, migration and invasion of lung cancer cells." (PMID 26919096, 2016). "It has been reported that HGF/c-Met signaling is important in EMT and metastasis and its downstream PI3k/Akt/mTOR signaling is one of the major pathways activated in cancer cells, including lung cancer cells." (PMID 26919096, 2016). "In this study, we find that hepatocyte growth factor (HGF) induces EMT, invasion and migration in A549 and 95D lung cancer cells, and these processes could be markedly inhibited by miR-206 overexpression." (PMID 26919096, 2016). "Our study has shown that HGF and EGF had a profound effect on the migration of lung cancer cells." (PMID 26310485, 2015). "However, recent reports to show that HGF can trans-activate EGFR and make the anti-EGFR therapy less effective or indeed make lung cancer resistant to EGFR therapy in lung cancer are very interesting indeed." (PMID 26310485, 2015). "Furthermore, the medicine is also shown to inhibit the migratory effect induced by a combination of HGF and EGF, an axis of evil in clinical lung cancer in which they work synergistically in stimulating the progression of lung cancers." (PMID 26310485, 2015).